KIAA0319L (KIAA0319 like)
Description:
Possible role in axon guidance through interaction with RTN4R. (Microbial infection) Acts as a receptor for adeno-associated virus and is involved in adeno-associated virus infection through endocytosis system.
Synonyms: AAVR; KIAA1837; AAVRL
Tractability: Antibody: UniProt places it where antibodies can reach, with high confidence; UniProt predicts a signal peptide or a membrane-spanning region; its Gene Ontology location is reachable by antibodies, with medium confidence. PROTAC: ubiquitination databases record sites on it; its protein half-life has been measured.
Gene: Protein-coding gene on chromosome 1 (35,393,883 to 35,557,950, reverse strand). Ensembl gene ENSG00000142687.
Subcellular location: Cytoplasmic granule membrane; Golgi apparatus membrane; Golgi apparatus, trans-Golgi network membrane; Cell membrane
Subcellular location (Human Protein Atlas): Golgi apparatus; Nucleoli
Gene Ontology:
Molecular function: protein binding
Biological process: neuron migration
Cellular component: cytoplasmic vesicle; Golgi apparatus; Golgi membrane; plasma membrane; trans-Golgi network membrane; membrane; endomembrane system; trans-Golgi network
Genetic constraint (gnomAD): Loss-of-function variants: 46 observed, 96.39 expected, observed/expected ratio (o/e) 0.48, 90% interval 0.38 to 0.61. The synonymous counts are far from expectation, so gnomAD's model fits this gene poorly and the ratio says little. Missense variants: 941 observed, 1,173.1 expected, observed/expected ratio (o/e) 0.8, 90% interval 0.76 to 0.85. Synonymous variants: 358 observed, 442.77 expected, observed/expected ratio (o/e) 0.81, 90% interval 0.74 to 0.88.
Homologues: Orthologues: chimpanzee KIAA0319L (99% identical), macaque KIAA0319L (97% identical), dog KIAA0319L (90% identical), pig KIAA0319L (90% identical), guinea pig KIAA0319L (88% identical), rabbit KIAA0319L (87% identical), mouse AU040320 (84% identical), rat KIAA0319l (83% identical), tropical clawed frog KIAA0319l (62% identical), zebrafish kiaa0319l (50% identical), Drosophila melanogaster CG7565 (32% identical), Caenorhabditis elegans Y55F3BR.2 (13% identical), and 2 more. Paralogues in human: KIAA0319 (48% identical), SPINT1 (8% identical), LRP11 (7% identical), WFIKKN1 (6% identical), WFIKKN2 (6% identical), AMBP (6% identical), TFPI2 (4% identical), TFPI (4% identical), WFDC8 (4% identical), SPINT2 (3% identical), EPPIN (2% identical), SPINT4 (2% identical), and 1 more.
Diseases named in the same sentence as KIAA0319L in open-access papers:
KIAA0319L is named in the same sentence as 11 diseases in open-access papers, as found by Europe PMC text mining. Sharing a sentence is not in itself a finding about the gene and the disease. The quoted sentences say what the papers report.
dyslexia (10 papers, 2013 to 2025). A learning disorder characterized by an impairment in processing written words. "Its paralogous gene, KIAA0319‐LIKE or KIAA0319L, has also been reported to be associated with dyslexia but with weaker evidence." (PMID 30950042, 2019). "The KIAA0319L gene has been described to have a putative association with dyslexia; surprisingly, we observed that homozygous KO males for AU040320, KIAA0319L ortholog, are infertile and present a globozoospermia-like phenotype." (PMID 29991750, 2018). "Interestingly, the paralogous gene KIAA0319L (or KIAA0319-Like), the only other member of this gene family, has also been linked to dyslexia." (PMID 29045729, 2017). "The second is KIAA0319L located on chromosome 1, which has been identified as a candidate for dyslexia." (PMID 24151499, 2013). "To investigate whether CU062 could interact with PKD domains from other proteins, we utilized the observation that the dyslexia-associated protein, KIAA0319-like protein (KIAA0319L), has five PKD domains in the range of 312–785 AAs." (PMID 37681898, 2023). "Consistent with the results from the binding assay, LAMP3 overexpression did not alter expression of dyslexia-associated protein KIAA0319-like protein (KIAA0319L, also named AAV receptor), a protein associated with AAV2 binding." (PMID 36329045, 2022).
Infertility (2 papers, 2018 to 2025). "Mutations in KIAA0319L could lead to human infertility; we screened for KIAA0319L mutations in a selected cohort of globozoospermia patients in which no genetic abnormalities have been previously identified, but detected no pathogenic changes in this particular cohort." (PMID 29991750, 2018).
Alzheimer disease (1 paper, 2024). A progressive, neurodegenerative disease characterized by loss of function and death of nerve cells in several areas of the brain leading to loss of cognitive function such as memory and language. "There are also studies on the relationship between genes and cognitive function that show that five genes, PFKFB4, PDK3, KIAA0319L, CEBPD, and PHC2T, have the potential to recognize Alzheimer’s disease." (PMID 39328989, 2024).
Globozoospermia (1 paper, 2018). Any structural anomaly of the acrosome resulting in a round sperm head. "After the identification of AU040320 as a new gene required for acrosome formation in mice, we explored the possibility that mutations affecting the homologous KIAA0319L gene could also cause globozoospermia in humans." (PMID 29991750, 2018). "The identification of the globozoospermia phenotype in mice after null mutations in the AU040320 gene suggested that mutations in KIAA0319L could also lead to globozoospermia in humans." (PMID 29991750, 2018). "In addition, we screened the homologous human KIAA0319L gene for putative pathogenic changes in a cohort of male patients with globozoospermia by sequencing individual exons but no mutations were identified in this particular cohort." (PMID 29991750, 2018). "Given the limited understanding of genetic mutations leading to globozoospermia in humans, we have also screened for exonic changes in KIAA0319L, in 16 patient samples already screened negative for deletions in the DPY19L2 gene, but have not found any pathogenic KIAA0319L mutation." (PMID 29991750, 2018).
Parkinson disease (1 paper, 2025). A progressive degenerative disorder of the central nervous system characterized by loss of dopamine producing neurons in the substantia nigra and the presence of Lewy bodies in the substantia nigra and locus coeruleus. "We speculated that the fusion of KIAA0319L and PARK7 results in a protein that integrates the endocytosis capabilities of KIAA0319L with PARK7, an enzyme mutated in hereditary Parkinson’s disease, potentially influencing SP-EPN_6 cellular responses to oxidative stress." (PMID 41160379, 2025).
KIAA0319L also shares sentences with these, for which no sentence is quoted: infection (13 papers); hearing loss (1); male infertility (1); neurological diseases (1); schizophrenia (1); viral infection (1).